MATK (megakaryocyte-associated tyrosine kinase)
Description:
Could play a significant role in the signal transduction of hematopoietic cells. May regulate tyrosine kinase activity of SRC-family members in brain by specifically phosphorylating their C-terminal regulatory tyrosine residue which acts as a negative regulatory site. It may play an inhibitory role in the control of T-cell proliferation.
Synonyms: CHK; CTK; HYL; HYLTK; Lsk; HHYLTK; DKFZp434N1212; MGC1708; MGC2101
Tractability: Small molecule: a high-quality ligand is known; it belongs to a druggable protein family. Antibody: its Gene Ontology location is reachable by antibodies, with medium confidence. PROTAC: ubiquitination databases record sites on it; its protein half-life has been measured; a small molecule that binds it is known.
Target class: Protein Kinase; Tyrosine protein kinase Csk family; TK protein kinase group; Enzyme; Kinase
Gene: Protein-coding gene on chromosome 19 (3,777,969 to 3,802,129, reverse strand). Ensembl gene ENSG00000007264.
Subcellular location: Cytoplasm; Membrane
Subcellular location (Human Protein Atlas): Microtubules; Centriolar satellite; Cytokinetic bridge; Cytosol; Mitotic spindle
Pathways (Reactome):
Signal Transduction: Downregulation of ERBB2 signaling
Gene Ontology:
Molecular function: protein binding; non-membrane spanning protein tyrosine kinase activity; protein tyrosine kinase activity; ATP binding; protein kinase activity
Biological process: positive regulation of cell population proliferation; protein phosphorylation
Cellular component: cytosol; plasma membrane; cytoplasm; membrane
Genetic constraint (gnomAD): Loss-of-function variants: 41 observed, 57.73 expected, observed/expected ratio (o/e) 0.71, 90% interval 0.55 to 0.92. The upper end of that interval is the gene's LOEUF score, 0.92, which puts it in group 3 of 6, group 1 being the genes least tolerant of losing a copy. Missense variants: 593 observed, 697.16 expected, observed/expected ratio (o/e) 0.85, 90% interval 0.79 to 0.91. Synonymous variants: 308 observed, 299.7 expected, observed/expected ratio (o/e) 1.03, 90% interval 0.94 to 1.13.
Homologues: Orthologues: chimpanzee MATK (96% identical), dog MATK (90% identical), pig MATK (90% identical), macaque MATK (89% identical), mouse Matk (87% identical), rat Matk (87% identical), guinea pig MATK (83% identical), tropical clawed frog matk (56% identical), zebrafish matk (55% identical). Paralogues in human: CSK (47% identical), ABL2 (36% identical), ABL1 (34% identical), FES (33% identical), SRC (33% identical), LCK (33% identical), YES1 (32% identical), FYN (32% identical), HCK (32% identical), BLK (32% identical), FGR (32% identical), SRMS (31% identical), and 20 more.
Diseases named in the same sentence as MATK in open-access papers:
MATK is named in the same sentence as 32 diseases in open-access papers, as found by Europe PMC text mining. Sharing a sentence is not in itself a finding about the gene and the disease. The quoted sentences say what the papers report.
diabetes (2 papers, 2008 to 2025). "Multivariate analysis showed that MATK levels (adjusted OR 0.492 [95% CI, 0.262–0.923], P = 0.027) were independently associated with WMH in patients with CCH adjusted for age, female, hypertension, diabetes mellitus, hyperlipidemia, smoking and drinking." (PMID 40933822, 2025).
osteosarcoma (2 papers, 2023 to 2024). A usually aggressive malignant bone-forming mesenchymal neoplasm, predominantly affecting adolescents and young adults. "It was established that the MMP2 gene acts as an upstream regulator of Src kinase activity by inhibiting its endogenous suppressor, CHK/MATK, in osteosarcoma cells." (PMID 39358756, 2024). "We show that enhanced osteosarcoma cell migration which is induced by sublethal concentrations of doxorubicin can be overcome by inactivating the MMP‐2 gene or overexpressing CHK/MATK." (PMID 38064181, 2023). "To investigate MMP‐2′s role in regulating the expression of endogenous Src inhibitors Csk and CHK/MATK in osteosarcoma, we analyzed gene fold expression and protein levels in U2OS WT and MMP‐2 KO cells." (PMID 38064181, 2023). "This is due to its role in suppressing on the gene and protein expression of the tumor suppressor CHK/MATK in osteosarcoma." (PMID 38064181, 2023). "In this study, we reveal that the MMP‐2 gene acts as an upstream regulator of Src kinase activity by suppressing its endogenous inhibitor, CHK/MATK, in osteosarcoma cells." (PMID 38064181, 2023). "Lastly, although a sublethal concentration of doxorubicin promotes osteosarcoma cell migration, combining this treatment with CHK/MATK overexpression in osteosarcoma cells hinders, or at least partially attenuates, cell migration." (PMID 38064181, 2023). "We also found that MMP‐2 regulates Src kinase activity via suppression of the endogenous Src inhibitor, CHK/MATK, in osteosarcoma cells." (PMID 38064181, 2023). "This study demonstrates that the MMP‐2 gene regulates Src kinase activity by suppressing CHK/MATK, an endogenous inhibitor of Src, in osteosarcoma cells." (PMID 38064181, 2023). "We also examined the phosphorylation level of Tyr‐527 to determine the inhibitory mechanism of CHK/MATK in osteosarcoma." (PMID 38064181, 2023). "To determine the effect of overexpressing CHK/MATK in osteosarcoma, we transduced WT cells with GFP‐MATK lentiviral particles and created a stable cell line." (PMID 38064181, 2023).
acute megakaryoblastic leukemia (1 paper, 2021). Acute megakaryoblastic leukemia (AMKL) is a form of acute myeloid leukemia (AML) that occurs predominantly in childhood and particularly in children with Down syndrome (DS-AMKL). "MATK encodes megakaryocyte-associated tyrosine kinase, which is structurally similar to C-terminal Src kinase; notably, megakaryocyte-associated tyrosine kinase is associated with acute megakaryoblastic leukemia." (PMID 34912812, 2021).
adenoma (1 paper, 2022). A neoplasm arising from the epithelium. "The results showed that BMX, HCK, and MATK were exclusively upregulated in the adenoma precursor cell population." (PMID 35221332, 2022). "Quantification of fluorescence intensity of double-positive cells showed that the levels of BMX, HCK, and MATK in adenoma were higher than those in normal tissues." (PMID 35221332, 2022). "The BMX+ or HCK+ or MATK+ E-cadherin+ double-positive cells presented in both normal tissue and matched adenoma were observed in 8, 11, and 7 of 20 patients, respectively." (PMID 35221332, 2022). "We then validated these results by probing BMX, HCK, and MATK, along with epithelial marker E-cadherin, in biopsies from healthy donors, normal tissues, and patient-matched adenoma tissues." (PMID 35221332, 2022). "Interestingly, in adenoma precursor cells, the genes that were hit in the PTK signaling also included the marker genes of adenoma precursor cells, such as BMX, MATK, and HCK." (PMID 35221332, 2022).
anaplastic large cell lymphoma (1 paper, 2021). Anaplastic large cell lymphoma (ALCL) is a rare and aggressive peripheral T-cell non-Hodgkin lymphoma, belonging to the group of CD30-positive lymphoproliferative disorders, which affects lymph nodes and extranodal sites. "CD30 and the megakaryocyte associated tyrosine kinase (MATK) are variably expressed and might be misleading, raising the diagnosis of anaplastic large cell lymphoma (ALCL) or monomorphic epitheliotropic intestinal T cell lymphoma (MEITL) and enteropathy associated T cell lymphoma (EITL)." (PMID 33808787, 2021).
Arterial stenosis (1 paper, 2025). Narrowing or constriction of the inner surface (lumen) of an artery. "It was found that in the WMH group, the expression of MATK in the group with cerebral artery stenosis <50% (26.2%) was significantly higher than that in the 50%–70% (52.4%) and >70% (21.4%) groups (P < 0.001)." (PMID 40933822, 2025). "Since the WMH patients we selected were all complicated with carotid artery stenosis or of middle cerebral artery stenosis along with cerebral hypoperfusion, we wanted to know the relationship between different arterial stenosis and MATK expression in CCH-WMH patients." (PMID 40933822, 2025).
autoimmune thyroid disease (1 paper, 2024). Inflammatory disease of the thyroid gland due to autoimmune responses leading to lymphocytic infiltration of the gland. "MATK, in the high expression group, demonstrated substantial enrichment in autoimmune thyroid disease, whereas in the low expression group, the chemokine signaling pathway exhibited predominant enrichment of MATK (Fig. 6C1, C2)." (PMID 38965390, 2024).
cerebral artery stenosis (1 paper, 2025). A cerebrovascular disorder characterized by an abnormal narrowing of a cerebral artery. "Interestingly, our results also found a significant negative correlation between decreased MATK expression and cerebral artery stenosis, suggesting that the correlation between MATK and WMH may be related to cerebral artery stenosis." (PMID 40933822, 2025).
colorectal cancer (1 paper, 2025). A primary or metastatic malignant neoplasm that affects the colon or rectum. "MATK is a protein that plays a role in regulating stemness and was found to be hypermethylated in colorectal cancer, which lowers its expression." (PMID 40358182, 2025). "MATK can inhibit SRC kinase activity and the loss of MATK is hypothesized to promote cancer progression in colorectal cancer." (PMID 40358182, 2025).
ear tumors (1 paper, 2021). "Therefore, MATK might be involved in the development of ear tumors that cause adaptive hearing loss." (PMID 34912812, 2021).
epilepsy (1 paper, 2021). A brain disorder characterized by episodes of abnormally increased neuronal discharge resulting in transient episodes of sensory or motor neurological dysfunction, or psychic dysfunction. "The PPI showed that there are six resistance genes (CD247, CTSW, IL2RB, MATK, NKG7, and PRF1) that may play a central role in the resistance of epilepsy patients." (PMID 34805265, 2021).
Hypertension (1 paper, 2025). The presence of chronic increased pressure in the systemic arterial system. "Univariate logistic regression analysis showed that age, hypertension, MoCA, and MATK were also associated with WMH." (PMID 40933822, 2025).
myopia (1 paper, 2019). "Additional genes related to myopia and identified in this study are MATK that has shown differential expression in the retinal cells of myopic patients." (PMID 30858441, 2019).
ovarian carcinoma (1 paper, 2020). A malignant neoplasm originating from the surface ovarian epithelium. "The expression intensity of MATK in ovarian cancer tissue was lower than that in normal tissue, but had a higher expression quantity, which cannot be clearly correlated with the polarity of our signature." (PMID 33271935, 2020).
pancreatic cancer (1 paper, 2020). "Alternatively, another signaling node of LYN in pancreatic cancer involves the megakaryocyte-associated tyrosine kinase (MATK)." (PMID 33233470, 2020). "In PANC-1 cells, MATK directly phosphorylates and inhibits LYN kinase to curb pancreatic cancer cell proliferation and invasion." (PMID 33233470, 2020).
tumor (7 papers, 2016 to 2025). "Megakaryocyte-associated tyrosine kinase (MATK) is positive in 87% of tumor cells in MEITL, and the extent of MATK expression has been reported to be useful for differentiating MEITL from EATL." (PMID 34830926, 2021). "However, the role of FGD3, TMEM176A, CD1B and MATK in anti‐tumor immunity remains unclear." (PMID 36814908, 2023).
cancer (6 papers, 2017 to 2025). A tumor composed of atypical neoplastic, often pleomorphic cells that invade other tissues. "The study's findings highlight the regulation of Src activation by MMP‐2 and its interaction with the endogenous Src inhibitor CHK/MATK, which presents new possibilities for targeted cancer therapies." (PMID 38064181, 2023). "The six upregulated genes (FCGR3A, LPAR5, MATK, MNDA, TMEM144, and CD84) play key immunomodulatory roles in cancer progression and metastasis." (PMID 40340807, 2025). "Additionally, the study demonstrates that sublethal concentrations of doxorubicin can promote cancer cell migration, but this effect can be countered by inactivating MMP‐2 and/or overexpressing CHK/MATK." (PMID 38064181, 2023). "Additionally, MATK has been related to cell invasion and IL4R expression in cancer cells seems to facilitate lymph node metastasis." (PMID 29285214, 2017).
MATK also shares sentences with these, for which no sentence is quoted: breast carcinoma (2 papers); asthma (1); dengue (1); enteropathy-associated T-cell lymphoma (1); glioblastoma (1); glioma (1); hearing loss (1); Hyperglycemia (1); hyperlipidemia (1); influenza (1); lung diseases (1); malaria (1); Middle cerebral artery stenosis (1); Obesity (1); Respiratory Disease (1).